TRBV5-5 (T cell receptor beta variable 5-5)
Description:
V region of the variable domain of T cell receptor (TR) beta chain that participates in the antigen recognition. Alpha-beta T cell receptors are antigen specific receptors which are essential to the immune response and are present on the cell surface of T lymphocytes. Recognize peptide-major histocompatibility (MH) (pMH) complexes that are displayed by antigen presenting cells (APC), a prerequisite for efficient T cell adaptive immunity against pathogens. Binding of alpha-beta TR to pMH complex initiates TR-CD3 clustering on the cell surface and intracellular activation of LCK that phosphorylates the ITAM motifs of CD3G, CD3D, CD3E and CD247 enabling the recruitment of ZAP70. In turn ZAP70 phosphorylates LAT, which recruits numerous signaling molecules to form the LAT signalosome. The LAT signalosome propagates signal branching to three major signaling pathways, the calcium, the mitogen-activated protein kinase (MAPK) kinase and the nuclear factor NF-kappa-B (NF-kB) pathways, leading to the mobilization of transcription factors that are critical for gene expression and essential for T cell growth and differentiation. The T cell repertoire is generated in the thymus, by V-(D)-J rearrangement. This repertoire is then shaped by intrathymic selection events to generate a peripheral T cell pool of self-MH restricted, non-autoaggressive T cells. Post-thymic interaction of alpha-beta TR with the pMH complexes shapes TR structural and functional avidity.
Synonyms: TCRBV5S3A2T; TRBV55; TCRBV5S5
Tractability: Antibody: UniProt places it where antibodies can reach, with medium confidence; UniProt predicts a signal peptide or a membrane-spanning region; its Gene Ontology location is reachable by antibodies, with medium confidence.
Gene: T-cell receptor variable (V) gene on chromosome 7 (142,482,548 to 142,483,019, forward strand). Ensembl gene ENSG00000211725.
Subcellular location: Cell membrane
Gene Ontology:
Biological process: cell surface receptor signaling pathway
Cellular component: plasma membrane
Homologues: Paralogues in human: TRBV5-7 (92% identical), TRBV5-6 (91% identical), TRBV5-4 (85% identical), TRBV5-3 (80% identical), TRBV5-1 (75% identical), TRBV9 (66% identical), TRBV13 (60% identical), TRBV7-9 (49% identical), TRBV11-2 (48% identical), TRBV11-3 (47% identical), TRBV7-6 (47% identical), TRBV7-7 (47% identical), and 39 more.